IL6 (interleukin 6)
Diseases named in the same sentence as IL6 in open-access papers (continued):
Sharing a sentence is not in itself a finding about the gene and the disease.
melanoma (continued). "Similarly, Cox2-dependent PGE2 can modulate the secretome of BrafV600E-expressing melanoma cells; loss of Cox2 was associated with reduced Il6 and Cxcl1, among other factors, consistent with our findings." (PMID 33730589, 2021). "However, other studies indicate that only cells with N-RAS mutation (changing Gln to Arg, which occurs in 15–20% of melanomas) constitutively express and release IL-1α, IL-6, and TNF-α into the medium." (PMID 34068679, 2021). "Indeed, signal transducer and activator of transcription 3 (STAT3) inhibition has been associated with a decreased level of IL-6 in melanoma and glioma cell lines." (PMID 33692796, 2021). "Thus, innate myeloid and neutrophil cells producing IL-6 and IL-8 are associated with a poor outcome with checkpoint blockade in melanoma, and both present a potential therapeutic target." (PMID 33827575, 2021). "Similar in many tumors, melanoma is also linked to the downstream IL‐6/STAT3 axis." (PMID 34531850, 2021). "In addition, in a melanoma model, a significant reduction in body weight loss was observed with IL-6 antagonist treatment." (PMID 32929072, 2020). "Circulating IL-6 has been associated with cancer progression and poor prognosis in melanoma, BC, and gastrointestinal tumors, among others, but only few studies have assessed IL-6 cellular origin." (PMID 33553157, 2020). "A vaccine composed of Hyper-IL6 (H16) gene-modified melanoma cells admixed with allogenic iPSCs was shown to cause superior extension disease-free survival, and long-term overall survival in melanoma-challenged C57BL/6 mice when compared to modified cells alone or H16 modified cells plus ESCs." (PMID 33266109, 2020). "In detail, B16F10 melanoma-bearing mice depicted skeletal muscle and epididymal fat mass reduction, muscle strength loss, and locomotor activity impairment, associated with elevated IL-6 levels in the plasma." (PMID 31569642, 2019). "Furthermore, an IL‐6/WNT5A positive feedback loop has been previously shown to be associated with the increased invasive migration of parental BRAFi‐sensitive melanoma cells." (PMID 30582770, 2019). "In melanoma, Wnt5a was associated with the release of IL-6, VEGF, and MMP2." (PMID 31510045, 2019). "To determine whether the increase in phosphorylated STAT3 was caused by extracellular IL-6 secreted by melanoma cells, we applied IL-6 antibodies to neutralize IL-6 in the medium." (PMID 28222747, 2017). "However, in vivo studies are needed to clarify the high rate of melanoma cell proliferation caused by the constitutive activation of STAT3 signaling resulting from XBP1s-driven IL-6 expression." (PMID 28222747, 2017). "Further, melanoma development is delayed in IL6 deficient mice." (PMID 24344100, 2013). "Furthermore, elevated levels of the proinflammatory proteins present in the “cytokine storm” linked to COVID‐19, such as TNF‐α, IL‐1α, IL‐1β, IL‐6, and ferritin, may have also caused skin depigmentation or hypopigmentation, ultimately resulting in melanoma." (PMID 40270775, 2025). "In addition, variants in the TNFA gene (-308 G/A) and IL6 have been identified in various cancers, such as melanoma and other solid tumors, that increase the production of pro-inflammatory cytokines, which may predict the increased severity of CRS." (PMID 40004863, 2025). "Moreover, in melanoma patients, high levels of IL-6 in the sera are associated with poor prognosis." (PMID 33287312, 2020). "First, CAFs secrete cytokines that favor melanoma invasion, including IL-6, IL-8, transforming TGF-β, β-catenin, fibroblast growth factor-2 (FGF-2), and VEGF." (PMID 40936894, 2025). "IL-6 can promote the proliferation, survival, and invasiveness of melanoma cells by activating the signal transducer and activator of transcription 3 (STAT3) signaling pathway." (PMID 41346595, 2025).
melanoma (continued). "Immature myeloid cells (MDSCs) are attracted by CSCs into the tumor, where they exert their immunosuppressive function and contribute to the maintenance of melanoma stemness by secreting factors such as IL-6 that activate the STAT3 pathway in tumor cells." (PMID 40806546, 2025). "The interaction between melanoma cells and microglia supports BM progression through melanoma-derived IL-6, which enhances STAT3 phosphorylation and SOCS3 expression in microglia, thereby aiding melanoma cell survival." (PMID 40076927, 2025). "In experiments where IL-6 and IL-8 were inhibited in melanomas, these interleukins were found to be essential for promoting the activity of CAFs." (PMID 41009413, 2025). "Further investigation by Linnskog revealed that IL-6 enhances the migratory and invasive abilities of melanoma cells by upregulating WNT5A expression via the p38α-mitogen-activated protein kinase pathway, thereby promoting tumor metastasis and spread." (PMID 40699636, 2025). "The analysis of cytokines from conditioned media of MeWo cells revealed a sevenfold induction of IL-8 and significant induction of other cytokines associated with melanoma progression and therapeutic resistance, such as GROα (CXCL1) and IL-6." (PMID 39658088, 2025). "Interleukin-6 (IL-6) is a multifunctional cytokine that is frequently overexpressed in the tumor microenvironment of melanoma." (PMID 41346595, 2025). "Elevations in circulating IL-6 and IL-17 following treatment were significantly correlated with irAEs in melanoma patients." (PMID 41239350, 2025). "It is noticeable that IL-17 can promote the growth of melanoma by up-regulation of IL-6 and the signal transducer and activator of transcription 3, demonstrating the possible involvement of Corynebacterium in the appearance of melanoma." (PMID 40431165, 2025). "In melanoma, IL-6 is related to poor prognosis and has been proposed as a potential checkpoint inhibition." (PMID 41268555, 2025). "MAFs are activated by melanoma cells through the secretion of cytokines and chemokines such as IL-6, FGF, and IL-8." (PMID 40136652, 2025). "In contrast, the levels of soluble IL-6 detected in samples collected at any timepoint from melanoma patients were significantly higher than controls (p < 0.01)." (PMID 40564098, 2025). "PD-1/PD-L1 blockade itself resulted in increased IL-6 production by TAMs, resulting in a dysfunctional Th1 T cell response against melanoma." (PMID 40762981, 2025). "In melanoma, SASP components such as IL‐6, IL‐8, and MMPs have been implicated in promoting angiogenesis, epithelial‐mesenchymal transition, and recruitment of MDSCs." (PMID 40926366, 2025). "Deleting IκBζ in melanoma abrogates the activity and chromatin association of STAT3 and NF-κB, thereby reducing the expression of the pro-proliferative cytokines IL-1β and IL-6, thus impairing melanoma cell growth." (PMID 40562773, 2025). "In melanoma, this activity in CAFs is promoted by increased expression of IL-1β, IL-6, IL-8, C-X-C motif chemokine ligand 8 (CXCL8), and various types of metalloproteinases." (PMID 40725022, 2025). "Beyond metabolic effects, adipocytes secrete adipokines (leptins, adiponectin, IL-6), which enhance cancer invasion in melanoma patients." (PMID 40136652, 2025). "The excessive IL-6 secreted by DCs stimulates STAT3 signaling in melanoma to upregulate MMP9 expression, thereby promoting tumor cell invasion." (PMID 40908470, 2025). "Our results demonstrated that CCNB1-high melanoma cells secrete elevated IL-6, a known activator of STAT3 signaling in NK cells." (PMID 40430484, 2025). "In a mice model with aggressive melanoma, IL-6 has been shown to alleviate T-reg-mediated immune responses for effective priming of cytotoxic CD8+ T-cells." (PMID 41376623, 2025). "Critically, treatment with an IL-6R inhibitor (100 μg/dose, total 5 doses) significantly decreased liver metastases of ceramide-MeWo cells, which indicates that stromal ceramide promotes melanoma liver metastasis via IL-6." (PMID 40280124, 2025).
melanoma (continued). "R.E treatment enhanced pathwaysassociated with immune activation, including upregulation of ISGssuch as IRF1, MX1, and CXCL1, as well as pro-inflammatory cytokinesincluding TNF and IL6 in melanoma cells." (PMID 41341044, 2025). "Specifically, plasma levels of IL-1α, IL-6, IL-17, and TNFα, proinflammatory cytokines, were significantly higher in the Melanoma + Combi-ICI group compared to controls." (PMID 40313772, 2025). "Conversely, blocking IL-6 in transgenic melanoma-bearing mice significantly accelerated tumor progression." (PMID 40636453, 2025). "In a RET transgenic melanoma mouse model, researchers identified a relationship between IL-6 levels, phosphorylated STAT3, and CCR5 expression in tumor-infiltrating MDSCs." (PMID 40636453, 2025). "Among melanomas, in situ lesions showed 11.39 ± 9.47pg/mL IL-6 serum compared to 6.43 ± 5.61pg/mL for invasive lesions (p=0.08), with similar concentrations to int-IL-6 (14.50 ± 1.90 vs. 14.23 ± 0.70pg/mL, p=0.6)." (PMID 41268555, 2025). "In a previous report we showed that senescence, induced by the DNA methylating agent temozolomide, increased the level of fusion proteins mitofusin 1 and 2 in melanoma, and silencing Mfn1 or Mfn2 expression reduced interleukin-6 secretion by senescent cells." (PMID 38195762, 2024). "In another study examining melanoma patients receiving ipilimumab, low IL-6 was found to be of prognostic value and was predictive of which patients developed irAEs." (PMID 38785743, 2024). "Consistent with our previous data, the dramatically elevated IL-6 levels measured in high-E2F1 melanoma cocultures substantially decreased under E2F1-KD." (PMID 39544930, 2024). "Conversely, combining CTLA-4 inhibitors with IL-6 inhibitors enhances the tumor microenvironment in malignant melanoma, leading to a significant reduction in tumor size and improved survival in mice." (PMID 39703501, 2024). "Accordingly, matrigel assays demonstrated that IL-6 treatment of shE2F1-expressing melanoma cells rescues their invasive capability, whereas addition of the IL-6 inhibitor led to the strongest reduction of cell motility." (PMID 39544930, 2024). "We performed iterative simulations modifying the values of E2F1 expression and found, that under basal STAT3 activation, increasing levels of E2F1 in melanoma cells can trigger the expression and secretion of IL-6." (PMID 39544930, 2024). "A mutant human IL-6 gene (c.370G > A translating to p.E124K [somatic missense]) was observed with melanoma in humans (COSMIC: observed in 2 of 78 samples)." (PMID 39336572, 2024). "The impact of activated E2F1-STAT3/IL-6 axis on melanoma-immune cell communication and its prognostic/therapeutic value was validated by mathematical modeling." (PMID 39544930, 2024). "Homozygous mutant mouse IL-6 gene (knockout) decreases the size of a melanoma that involves transgenic human c-RET protein in mouse skin." (PMID 39336572, 2024). "Our simulations suggest that high levels of IL-6 secretion by melanoma cells can be either achieved through high levels of E2F1, high levels of STAT3, or moderate levels of both TFs." (PMID 39544930, 2024). "In summary, we conclude that an MLR with CD3+ T cells recapitulates the correlation of increased IFN-α and IL-6 with reduced T cell responses in melanoma patients." (PMID 38967829, 2024). "Melanoma cells exhibit a considerable increase in the pro-inflammatory IL-6 gene due to TNFα/TNFR1 signaling and TNF-α overexpression." (PMID 38398617, 2024). "This interplay between miR-98 and IL-6 via the Stat3-NF-κB-lin28B pathway is indicative of a complex regulatory mechanism influencing melanoma progression." (PMID 38872210, 2024). "Th17 Tregs have been previously found to promote melanoma progression through activation of the IL-6/STAT3 pathway." (PMID 38426087, 2024).
melanoma (continued). "This is consistent to prior observations showing that patients with melanoma receiving immune checkpoints blockade have IL-6 upregulation 54, 55, which mediates immune-related adverse effects." (PMID 38505617, 2024). "Studies have demonstrated that high serum levels of IL-6 correlate with reduced overall survival in melanoma patients, highlighting its potential as a prognostic marker." (PMID 39200315, 2024). "On the other hand, different authors have consistently maintained that EDPs induce the production and/or secretion of IL-1α, IL-1β, and IL-6 in ligamentum flavum cells, synovial cells, and melanoma cell lines." (PMID 38967692, 2024). "Melanoma-derived CFFs, however, showed the highest level of IL-6, followed by pancreatic adenocarcinoma cells." (PMID 38698774, 2024). "Anti-IL-6 enhances Th1 immune responses and decreases PD-L1 levels and melanoma development in mice." (PMID 38505617, 2024). "Untreated melanoma and renal cell carcinoma patients with newly detected metastases had, in general, a serum IL-6 concentration within the normal range, but PBMCs from these patients produced large amounts of IL-6." (PMID 39518029, 2024). "Consistently, upregulation of E2F1 and IL-6 positively correlates with tumor infiltration of immunosuppressive Th2 cells in melanoma patients." (PMID 39544930, 2024). "We demonstrate that high levels of E2F1 in melanoma cells disrupt the balance regulated by various cytokines/interleukins such as IL-6." (PMID 39544930, 2024). "Previous studies have shown that melanoma cells with Wnt5a knockdown secrete lower levels of IL-6 compared to control cells 30, and activation of Wnt5a signaling in these cells enhanced IL-6 expression." (PMID 39440046, 2024). "In contrast to monocultured CD8+ or CD4+ T cells, metastatic melanoma cells showed a high IL-6 concentration in the supernatant." (PMID 39544930, 2024). "While the expression of IL6 and IL8 is associated with early melanoma, TGFβ, IL1 and GM-CSF are highly secreted by advanced melanoma cells, with TGFβ being diagnostic of patient metastasis." (PMID 39494336, 2024). "In this study, we have found that downregulation of RIPK4 using two different techniques, siRNA and CRISPR/Cas9, inhibits IL-8 and IL-6 production in two melanoma cell lines, WM266.4 and A375." (PMID 38656555, 2024). "IL-6 and IL-8 serum concentrations of melanoma patients have been found to be predictive of response to immunotherapies and to correlate with poor prognosis." (PMID 37345186, 2023). "Mohapatra and colleagues investigated the mechanism according to which IL-6 was related to increased invasiveness in BRAF V600E melanoma cells." (PMID 37627054, 2023). "Although higher IL-6 levels are reportedly associated with worse OS and PFS in patients with melanoma and non-small-cell lung carcinoma undergoing ICI, reports on patients with UC are lacking." (PMID 38026978, 2023). "In the endogenous WNT5A low expressed melanoma cells, the stimulation with rWNT5A led to a great release of EVs carrying the immunoregulatory cytokine IL-6, and more important the pro-angiogenic agents, including IL-8, VEGF and MMP2." (PMID 37575250, 2023). "IL6 signalling is an important modulator of inflammation, immune response and tumour progression, and high level of IL6 in blood samples was correlated to worse outcome in melanoma, renal cell carcinoma and other cancer types." (PMID 37551424, 2023). "The current iteration of AGI-101H incorporates two melanoma cell lines retrovirally transduced with a designer cytokine gene known as Hyper-IL6 or H6, which serves as a molecular adjuvant." (PMID 37681891, 2023). "An increase of IL-6 secretion was observed in the melanoma cell line A2058 after stimulation with 1 μg/ml LPS." (PMID 37292297, 2023). "For example, α-pinene inhibits the production of pro-inflammatory cytokines, such as TNF-α (Tumor Necrosis Factor α) and IL-6 (Interleukin 6), in melanoma cells." (PMID 37515699, 2023).
melanoma (continued). "The adipocytes in obese individuals produce less adiponectin, which is anti-neoplastic, and more leptin and cytokines, including interleukin 6, interleukin 8, and transforming growth factor-β, which can increase melanoma and NMSC growth and metastasis." (PMID 37777736, 2023). "The response of melanoma cells to IL-6 in the co-culture was the fastest in M12.CB3 and M16.CB3 cells." (PMID 37296634, 2023). "We profiled the IL-12 virotherapy-induced immune equilibrium in murine melanoma, identifying blockade of innate inflammatory cytokines, tumor necrosis factor alpha (TNFα), IL-1β, or IL-6 as possible synergistic interventions." (PMID 37461742, 2023). "The combination of the anti-IL-6-antibody tocilizumab with immune checkpoint inhibition for the treatment of unresectable melanoma is currently being tested in a clinical trial (NCT03999749)." (PMID 35841421, 2023). "It has also been reported that the TLR-2-mediated secretion of IL-6 is responsible for the anti-tumor function of MCs against melanoma and lung cancer, both in vitro and in vivo." (PMID 37376140, 2023). "An autoinflammatory loop has been reported in melanoma, where tumor cells produce IL-1β and IL-6 through IL-1β/IL-6/STAT3 axis allowing for the activation of MDSCs." (PMID 36932407, 2023). "The influence of IL-6 on the proliferation of melanoma and microglia cells in 3D co-cultures was also heterogeneous." (PMID 37296634, 2023). "Induces anti-cancerous effect by activating dendritic cells, antigen-specific T cells in the C57BL/6 rodents, and releases pro-inflammatory cytokines such as TNF-α, IL-12 and IL-6 in B16 melanoma cells." (PMID 37215217, 2023). "It has also been reported that interferon-γ, and interleukin-6 and -10 in advanced melanoma were significantly higher in the patients with response to nivolumab treatment." (PMID 36745657, 2023). "We further showed that BET inhibitors sensitize melanoma cells to sunitinib by repressing GDF15 expression in a direct way by targeting its promoter or indirectly by targeting the IL6/STAT3 axis." (PMID 36720918, 2023). "Constitutively activated NLRP3 in melanoma secretes IL-1β that initiates IL-6 secretion through stimulating IL-1R." (PMID 36932407, 2023). "Subsequently, we measured the IL6 concentration in the supernatant using an ELISA kit and found that the IL6 concentration was markedly reduced in melanoma cells after BET inhibitor treatment." (PMID 36720918, 2023). "Exposure of melanoma cells to MGCM resulted in upregulated levels of IL-6 secreted from M12.CB3 and M16.CB3 cells, compared to the basal levels of secreted IL-6 from naïve (control) melanoma cells." (PMID 37296634, 2023). "BRD2 and BRD4 are overexpressed in human primary and metastatic melanomas, and their inhibition results in downregulation of IL-6 and IL-8." (PMID 36711038, 2023). "Several cytokines, including monocyte chemoattractant protein 1 (MCP-1), TNF-α, IL-6 and IL-2 have been reported to be predictive biomarkers for the response of melanoma patients to ICI treatment or for melanoma metastases." (PMID 36768978, 2023). "In the classic B16-F10 melanoma model, known for its high metastatic potential, we observed that IL-6 (mainly derived from the melanoma cells) promotes the release of glutathione (GSH) from hepatocytes to the circulating blood." (PMID 36766760, 2023). "Adipocytes cocultured with melanoma cells secreted higher IL6 and SerpinE1 levels and produced less CCL2, CXCL1, and angiogenic molecules." (PMID 37481560, 2023). "IL-6 is dysregulated in many types of cancers, and increased serum levels of IL-6 have been correlated with a worse prognosis in patients bearing different cancers, including melanoma." (PMID 36766760, 2023). "IL-6 addition to three melanoma-microglia co-cultures resulted in enhanced proliferation of both melanomas as well as microglia cells." (PMID 37296634, 2023).